MYCN (MYCN proto-oncogene, bHLH transcription factor)
Diseases named in the same sentence as MYCN in open-access papers (continued):
Sharing a sentence is not in itself a finding about the gene and the disease.
neuroblastoma (continued). "In contrast, ALK amplification was not a statistically independent marker for survival in models with MYCN, stage and age in a meta-analysis, combining a new series of 254 neuroblastomas and 455 published cases from 3 other cohorts." (PMID 29156716, 2017). "In another study, the importance of alternative splicing following high-level amplification of the MYCN gene in neuroblastoma has been explored." (PMID 28206967, 2017). "Considering the significance of MYCN in neuroblastoma, our observation that MYCN was the top downregulated transcript in serum-grown PDX cells is intriguing." (PMID 28860499, 2017). "In neuroblastoma, MYCN-amplification is the most consistent genetic aberration associated with poor prognosis and treatment failure." (PMID 28358317, 2017). "An appealing strategy to treat patients with tumors expressing high MYCN levels, including MYCN-amplified neuroblastoma, consist of developing immune therapies based on vaccination against MYCN protein as a tumor-associated antigen." (PMID 28358317, 2017). "In a MYCN transgenic mouse model, loss of one allele of PTEN promoted tumor growth, illustrating the potential role of PTEN in neuroblastoma pathogenesis." (PMID 28881723, 2017). "In contrast, another study with 87 neuroblastoma patients, investigators reported 3 mutations in TIAM1 gene, one with concomitant MYCN amplification and poor outcome." (PMID 28423360, 2017). "Similar results were also obtained in neuroblastoma, where ectopic expression of AHR was found to downregulate MYCN (specific malignant factor of neuroblastoma) and E2F1 expression and correlated highly with the histological grade of differentiation." (PMID 27752740, 2017). "A human NCSC model was generated in which inducible MYCN triggered an immortalized phenotype capable of forming metastatic neuroectodermal tumors in mice, resembling human neuroblastoma." (PMID 29238067, 2017). "Using mass spectrometry-based metabolomics, the authors performed global metabolic profiling of MYCN-driven neuroblastoma at multiple time-points representing hyperplastic ganglia, early tumors, and advanced tumors." (PMID 28443280, 2017). "First, we determined if MYCN regulates AKAP1 expression in neuroblastoma cells, where MYCN is critical to oncogenesis." (PMID 28569781, 2017). "The relative expression levels of NDRG1, LSD1 and MYCN were further analyzed in neuroblastoma patients." (PMID 27894074, 2017). "As well as MYCN amplification, activating point mutations of ALK and NRAS are associated with high-risk and relapsing neuroblastoma." (PMID 28602975, 2017). "In all patients with a MYCN-amplified neuroblastoma, MYCN copy numbers determined using cfDNA were lower than those determined from tumor gDNA." (PMID 29156716, 2017). "For example, ALK mutations are frequently observed in MYCN-amplified neuroblastomas, and most of ALK amplifications co-occur with MYCN amplification." (PMID 28425916, 2017). "Although the most frequent alteration in neuroblastoma is the amplification of MYCN, it's difficult to target MYCN directly." (PMID 28055978, 2017). "In neuroblastoma with MYCN-amplification, copy number aberrations have been observed in genes regulating the G1 phase of the cell cycle." (PMID 28358317, 2017). "The presence of MYCN is required to complete the differentiation process of neuroblastoma cells treated with retinoic acid, since an increase of expression as an early event followed by a later reduction is indispensable to fulfill the differentiation process." (PMID 28358317, 2017). "We also find that neuroblastoma cell lines with ALK aberrations develop resistance to ALK inhibition as a result of MYCN upregulation." (PMID 28425916, 2017). "Our previous work discovered a survival mechanism by which MYCN-amplified neuroblastoma circumvents cell death by upregulating components of the error-prone non-canonical alternative nonhomologous end-joining (alt-NHEJ) DNA repair pathway." (PMID 29238067, 2017).
neuroblastoma (continued). "These datasets revealed that TGFB1 was also a top regulator of the differences in the MYCN regulator and effector networks between single copy MYCN and MYCN-amplified neuroblastoma cell lines." (PMID 28187790, 2017). "By applying global omics approaches to the signalling networks regulating neuroblastoma differentiation and stemness, we have determined the pathways involved in the MYCN-mediated retinoid resistance, with TGF-β signalling being a key regulator." (PMID 28187790, 2017). "Here we evaluated the ability of GSK461364 to inhibit neuroblastoma cell viability and proliferation and to induce death in cell lines with different MYCN copy number backgrounds, and to suppress xenograft tumor growth in nude mice." (PMID 28036269, 2017). "About 20% of neuroblastoma cases are characterized by MYCN gene amplification, which has been correlated with tumor progression and is routinely used as a clinical biomarker for treatment stratification." (PMID 28525978, 2017). "This is exemplified by MYCN oncogene targets that balance proliferation, differentiation, and cell death similarly in normal NCSC and in high-risk neuroblastoma." (PMID 29238067, 2017). "The PI3K/mTOR inhibitor NVP-BEZ235 selectively killed MYCN-expressing neuroblastoma tumor cells through apoptosis and concomitantly eliminated MYCN protein in vivo." (PMID 28333115, 2017). "MYCN amplification and 11q deletion are two inversely correlated prognostic factors of poor outcome in neuroblastoma." (PMID 28924153, 2017). "While the original zebrafish neuroblastoma models were based on the overexpression of human MYCN, a recent variation combined MYCN overexpression under the dopamine-β-hydroxylase (dβh) promoter with expression of mutated human ALK." (PMID 28894696, 2017). "Although artificial, this scenario mirrors highly amplified MYCN neuroblastoma where over 70 additional copies of the MYCN gene can be inserted in the tumour’s genome, often losing their endogenous promoters and enhancers." (PMID 28187790, 2017). "We have shown that co-targeting of the retinoic acid and TGF-β pathways, through RA and KGN (a small molecule TGF-β activator) combination treatment, strongly reduces MYCN-amplified RA-resistant neuroblastoma cell viability." (PMID 28187790, 2017). "Cytotoxic T lymphocytes generated using a MYCN-derived peptide containing a HLA-A1 binding motif were able to lyse HLA-matched, MYCN-amplified neuroblastoma tumor cells in vitro." (PMID 28358317, 2017). "Our findings in the neuroblastomas of MYCN PTEN+/− mice further validate the role of PTEN in the potential pathogenesis of human neuroblastoma." (PMID 28881723, 2017). "Here we report a comprehensive characterization of two MYCN amplified neuroblastoma PDX-derived cell lines, named LU-NB-2 and LU-NB-3." (PMID 28860499, 2017). "MYCN inhibition has previously been proposed to promote neuroblastoma cell differentiation, and we therefore treated LU-NB-3 cells with the MYC-MAX inhibitor 10058-F4." (PMID 28860499, 2017). "In Wilms tumor and neuroblastoma, MycN binds to the E-box II at CRABP-II promoter and promotes its expression." (PMID 28881741, 2017). "Replication stress was recently also detected upon olaparib treatment of MYCN-amplified neuroblastoma, which also express high PARP1/2 levels." (PMID 29262611, 2017). "To this end, we transcriptionally profiled (RNA-seq) ATRA (from here on referred to as RA) exposed neuroblastoma cells in the presence of high and low MYCN expression levels and performed network-based precision medicine analysis." (PMID 28187790, 2017). "Some of them, including 10058-F4 and 10074-G5, have, in addition, also been identified to target MYCN and to induce neuroblastoma cell differentiation and apoptosis." (PMID 28358317, 2017).
neuroblastoma (continued). "In patients with localized neuroblastoma age 18 months or older, especially in INRG high-risk patients harboring MYCN amplification, extended surgery of the primary tumor site improved local control rate and survival with an acceptable risk of complications." (PMID 28778185, 2017). "The activation of this pathway was highly selective in discriminating MYCN-amplified neuroblastomas in all three datasets." (PMID 29137381, 2017). "It has been shown that MYC upregulates expression of Aurora kinases A and B in neoplasms, and that Aurora kinase A is known to stabilize MYCN protein in neuroblastoma." (PMID 28333115, 2017). "Among them, our group showed that 10058-F4 is able to induce increased survival in TH-MYCN mice, and the treatment delayed tumor growth in a MYCN-amplified neuroblastoma xenograft." (PMID 28358317, 2017). "As with prostate cancer, AURKA has been linked to the disease but its inhibition does not alter MYCN levels, suggesting a difference in activity in MYCN-amplified non-small lung cancer cells (NSCLC) compared to MYCN-amplified neuroblastoma and prostate cancer." (PMID 28358317, 2017). "To this end, we monitored the relative levels of AKAP1 protein and RNA in the human Tet-21/N neuroblastoma cell line conditionally expressing MYCN under the control of a Tet-Off (tetracycline) promoter." (PMID 28569781, 2017). "In contrast, induction of MYCN in neuroblastoma-derived cells was accompanied by a much more substantial accumulation of REV-ERBα." (PMID 28332490, 2017). "When MYCN-amplified neuroblastoma cells were deprived of glutamine, the TCA cycle intermediates were depleted and cells underwent cell death." (PMID 28358317, 2017). "As neuroblastoma cells can be induced to differentiate even in the presence of a certain level of MYCN overexpression, we investigated KGN-RA combination treatments in the MYCN-amplified and RA-resistant IMR32 cell line." (PMID 28187790, 2017). "The Cre-conditional human MYCN-driven neuroblastoma mouse model, in which MYCN is conditionally expressed in dopamine β-hydroxylase-expressing cells in the neural crest, further supports the role of MYCN in neuroblastoma origination and development." (PMID 28358317, 2017). "Of note, ODC1 which is located within 5 Mb of MYCN is co-amplified with MYCN in 15–20% of MYCN-amplified neuroblastomas and ODC1 is significantly overexpressed in those tumors, thus presenting the first example of oncogene-target gene co-amplification." (PMID 29240775, 2017). "Alisertib is of particular interest for neuroblastoma due to preclinical efficacy in xenograft models and the discovery that Aurora A Kinase stabilizes the oncogene MYCN." (PMID 28147331, 2017). "RKIP is a Raf-inhibitory protein that regulates MYCN activation, is transcriptionally upregulated by didymin, and appears to play a key role in the anti-neuroblastoma actions of didymin." (PMID 28187004, 2017). "By applying genomic-level omics approaches to the signalling networks regulating neuroblastoma differentiation and stemness, we have determined the regulators involved in the MYCN-mediated inhibition of neuroblastoma cell differentiation." (PMID 28187790, 2017). "Together, these findings suggest that ML327 suppresses MYCN levels within neuroblastoma xenografts and induces cell death within xenografts." (PMID 29207623, 2017). "Given that the Kelly neuroblastoma cell line is dependent on continued expression of MYCN, we tested its sensitivity to EP400 depletion." (PMID 29028833, 2017). "We altered MYCN expression levels in a MYCN-inducible neuroblastoma cell line to facilitate or block retinoic acid (RA)-mediated neuronal differentiation." (PMID 28187790, 2017). "To validate the identified MYCN-specific gene expression pathway, we collected 41 unrelated neuroblastoma clinical samples, including 5 MYC–amplified and 36 wild type tissue blocks." (PMID 29137381, 2017).
neuroblastoma (continued). "Specifically, we found that, for MYCN amplified neuroblastoma, pairwise expression of ACVR2B or anaplastic lymphoma kinase (ALK) with GFRA3, GFRA2, Cadherin 24, or with one another provided the strongest hits." (PMID 28871274, 2017). "At first, the role of Notch pathway components was investigated in neuroblastoma cell lines with different MYCN gene amplification degree, which is related to aggressiveness and malignant phenotype." (PMID 28525978, 2017). "Furthermore, it was found that MYCN-enriched cell lines and sensitive cells mostly overlapped, while MYCN-nonamplified cells and resistant cells partially overlapped, indicating that MYCN level was positively associated with the sensitivity of neuroblastoma cells to ribociclib treatment." (PMID 28438180, 2017). "In this study, the DLL1 ligand was identified as the Notch pathway component highly expressed in neuroblastoma cells with MYCN amplification." (PMID 28525978, 2017). "We have recently independently shown that Wnt and MAPK signalling are involved in regulating differentiation in MYCN-amplified neuroblastoma cells." (PMID 28187790, 2017). "For this, MYCN PTEN+/+ and MYCN PTEN+/− neuroblastoma cells were implanted into the flank of nude mice and tumor growth was monitored for 30 days." (PMID 28881723, 2017). "To assess quality of the MYCN amplification pathway in discriminating the experimental MYCN -amplified and wild type neuroblastoma samples, we calculated this pathway activation strength (PAS) according to the OncoFinder method." (PMID 29137381, 2017). "In the current study, we demonstrated that LSD1 in cooperation with MYCN controls cell migration and invasiveness of neuroblastoma cells through transcription regulation of the metastatic suppressor NDRG1." (PMID 27894074, 2017). "We set out to evaluate ddPCR for use with patient blood plasma samples and determine its accuracy and sensitivity for detecting neuroblastoma-specific MYCN copy number variation in cell-free DNA (cfDNA)." (PMID 29156716, 2017). "In this study we further investigated the role of Notch signaling and identified Delta-like 1 (DLL1) as a novel molecular target in neuroblastoma cells with a high degree of MYCN amplification, which is a major oncogenic driver in neuroblastoma." (PMID 28525978, 2017). "Our studies unravel a critical role for HDAC11 in cell cycle progression and viability of MYCN-amplified neuroblastoma cells." (PMID 28252645, 2017). "These tumors are histologically and genetically very similar to aggressive undifferentiated human neuroblastoma, resembling the pathological and imaging characteristics, MYCN transgene amplification and tumor–stroma interactions." (PMID 28358317, 2017). "Taken together, our data illustrate an important role for HDAC11 in cell cycle progression and viability of MYCN-amplified neuroblastoma cells, and illuminates HDAC11 as a potential novel drug target for this subgroup of high-risk neuroblastomas." (PMID 28252645, 2017). "Although MYCN amplification with overexpression was observed in neuroblastoma, sarcoma, and lung cancer, our study identified that MYCN was amplified and overexpressed in 13% of liver cancer samples." (PMID 28377632, 2017). "In neuroblastoma cells in which the oncogene MYCN is amplified, eEF2K is also activated and is required for these cells to survive nutrient withdrawal, as shown by the observation that they are very sensitive to the eEF2K inhibitor A-484954." (PMID 29186827, 2017). "Over the last 20 years, there has not been great improvement in the overall survival of children with MYCN-amplified neuroblastoma." (PMID 28035057, 2017). "We determined the signalling networks through which RA mediates neuroblastoma differentiation and the inhibitory perturbations to these networks upon MYCN overexpression." (PMID 28187790, 2017).
neuroblastoma (continued). "Inhibitors for the PI3K/mammalian target of rapamycin (mTOR)/AKT axis lead to increased GSK3ß activity and, thus, to increased MYCN protein degradation, inducing growth arrest and apoptosis in neuroblastoma cells both in vitro and in vivo." (PMID 28358317, 2017). "NDRG1 was originally identified as a major target gene repressed by the transcription factor MYCN (also named N-Myc) in neuroblastoma cells." (PMID 28981455, 2017). "Transient HDAC11 knockdown in the SH-SY5Y and SK-N-AS neuroblastoma cell lines, which lack MYCN amplification, diminished ATP content by 21–38%." (PMID 28252645, 2017). "Together, these results showed that SGO1 is elevated in MYCN- or MYC-overexpressing cancers, including neuroblastoma cell lines showing MYCN amplification." (PMID 27539729, 2016). "MYCN is amplified in ~25% of cases of neuroblastoma, the most common extracranial solid tumor seen during childhood, and MYCN amplification correlates with poor prognosis." (PMID 27539729, 2016). "Our findings altogether suggest that MYCN and differentiation-inducing miRNAs form an interaction network that play an important role in neuroblastoma tumorigenesis through regulating cell differentiation." (PMID 27764804, 2016). "MYCN amplification is the most common genetic alteration in neuroblastoma and plays a critical role in neuroblastoma tumorigenesis." (PMID 27764804, 2016). "Genetic abnormalities, including DNA ploidy and amplification of the MYCN oncogene, which is observed in about 20% of neuroblastoma cases, also play a role in determining the tumor phenotype and predicting the outcome." (PMID 27669225, 2016). "Our further analysis of the neuroblastoma specimens shows that expression of miR-137 was significantly anti-correlated with MYCN mRNA expression in neuroblastoma specimens." (PMID 27764804, 2016). "Our data argue a role for HDAC5 in transcriptionally repressing CD9 in neuroblastoma cells beyond the repression achieved by MYCN and DNA methyltransferases, and offers an avenue for pharmacological intervention." (PMID 27572323, 2016). "The fusion gene also reduced MNA neuroblastoma cell viability with MYCN single copy SY5Y cells being more resistant, demonstrating a selective deleterious role of ectopic Wnt pathway hyper-activation in MNA neuroblastoma cells." (PMID 27531891, 2016). "In a previous study, we used microarray data (GEO accession: GSE43419) to identify genes induced during progression of neuroblastoma in MYCN-Tg mice." (PMID 27539729, 2016). "The final patient studied was a 32-week preterm infant diagnosed with stage 4S neuroblastoma and MYCN amplification, being treated at 8 weeks of age (gestational age of 40 weeks)." (PMID 26875154, 2016). "MCL-1 reduction by siRNA sensitized MYCN-amplified neuroblastoma cells to ABT-199, inducing similar levels of apoptosis as the combination treatment in the scrambled (sc) siRNA transfected cells." (PMID 26859456, 2016). "The specific CDK4/6 inhibitor, ribociclib/LEE011, reduced proliferation in MYCN-amplified neuroblastoma in vitro and decreased growth of murine neuroblastoma xenografts." (PMID 26771642, 2016). "Aurora kinase A inhibitors offer a promising new direction for treatment of neuroblastoma, particularly in MYCN-amplified neuroblastomas given the relationship between Aurora kinase A and N-MYC." (PMID 26771642, 2016). "We next treated MYCN-amplified neuroblastoma cells with a short time course of MLN8237, and found p4E-BP1 and MCL-1 were reduced prior to marked mitotic arrest, suggesting a contribution of MCL-1 downregulation independent of mitotic arrest." (PMID 26859456, 2016). "The activity of NVP-BEZ235 and Torin1 against Kelly and three additional MYCN-amplified neuroblastoma cell lines correlated with induction of apoptosis in the Kelly cell line by two independent assays." (PMID 27438153, 2016).